H2AC11 (H2A clustered histone 11)
Description:
Core component of nucleosome. Nucleosomes wrap and compact DNA into chromatin, limiting DNA accessibility to the cellular machineries which require DNA as a template. Histones thereby play a central role in transcription regulation, DNA repair, DNA replication and chromosomal stability. DNA accessibility is regulated via a complex set of post-translational modifications of histones, also called histone code, and nucleosome remodeling.
Synonyms: H2AFP; HIST1H2AG; pH2A/f; H2A/p; H2A.1b; H2AG
Gene: Protein-coding gene on chromosome 6 (27,133,043 to 27,135,292, forward strand). Ensembl gene ENSG00000196787.
Subcellular location: Nucleus; Chromosome
Subcellular location (Human Protein Atlas): Nucleoplasm
Pathways (Reactome):
Chromatin organization: HATs acetylate histones; HDACs deacetylate histones; RMTs methylate histone arginines
Disease: Dengue Virus-Host Interactions; HCMV Early Events; HCMV Late Events
Metabolism of proteins: Metalloprotease DUBs; UCH proteinases; Ub-specific processing proteases
Gene Ontology:
Molecular function: enzyme binding; protein binding; structural constituent of chromatin; DNA binding; protein heterodimerization activity
Biological process: chromatin organization; heterochromatin formation
Cellular component: extracellular exosome; nucleoplasm; nucleosome; nucleus; chromosome
Genetic constraint (gnomAD): Loss-of-function variants: 8 observed, 6.47 expected, observed/expected ratio (o/e) 1.24, 90% interval 0.71 to 1.87. That is too few expected variants to judge how well the gene tolerates losing a copy. Missense variants: 189 observed, 190.44 expected, observed/expected ratio (o/e) 0.99, 90% interval 0.88 to 1.12. Synonymous variants: 161 observed, 86.98 expected, observed/expected ratio (o/e) 1.85, 90% interval 1.62 to 1.98.
Homologues: Orthologues: chimpanzee H2AC15 (100% identical), dog H2AC13 (100% identical), macaque H2AC17 (100% identical), Drosophila melanogaster His2A:CG31618 (85% identical), Drosophila melanogaster His2A:CG33808 (85% identical), Drosophila melanogaster His2A:CG33814 (85% identical), Drosophila melanogaster His2A:CG33817 (85% identical), Drosophila melanogaster His2A:CG33820 (85% identical), Drosophila melanogaster His2A:CG33823 (85% identical), Drosophila melanogaster His2A:CG33826 (85% identical), Drosophila melanogaster His2A:CG33829 (85% identical), Drosophila melanogaster His2A:CG33832 (85% identical), and 11 more. Paralogues in human: H2AC13 (100% identical), H2AC15 (100% identical), H2AC16 (100% identical), H2AC17 (100% identical), H2AC7 (99% identical), H2AC12 (98% identical), H2AC18 (98% identical), H2AC19 (98% identical), H2AC4 (98% identical), H2AC6 (98% identical), H2AC8 (98% identical), H2AC14 (98% identical), and 15 more.
Diseases named in the same sentence as H2AC11 in open-access papers:
H2AC11 is named in the same sentence as 2 diseases in open-access papers, as found by Europe PMC text mining. Sharing a sentence is not in itself a finding about the gene and the disease.
H2AC11 shares sentences with these, for which no sentence is quoted: COVID-19 (1 paper); tumor (1).